KLK5 (kallikrein related peptidase 5)
Diseases named in the same sentence as KLK5 in open-access papers (continued):
Sharing a sentence is not in itself a finding about the gene and the disease.
ovarian carcinoma (27 papers, 2001 to 2024). A malignant neoplasm originating from the surface ovarian epithelium. "It is worth noting that KLK5 is associated with vaginal cancer, cutaneous squamous cell carcinoma (cSCC), ovarian cancer, endometrial cancer, ESCC, breast cancer, prostate cancer, uterine cervical cancer, colorectal adenoma-carcinoma and ovarian cancer." (PMID 35223512, 2022). "Kallikrein-related peptidase 5 (KLK5) is implicated in tumor progression, and its expression seems to impact the prognosis of several solid tumors such as ovarian cancers." (PMID 36675955, 2022). "In ovarian cancer, overexpression of KLK5 protease in tumor tissues is associated with more advanced stages and grade of the disease." (PMID 34201422, 2021). "Positive correlation of KLK5 expression with increased risk for relapse and death in ovarian cancer was illustrated as well." (PMID 32076707, 2020). "In ovarian cancer, overexpression of KLK5 protease in tumor tissues is associated with more advanced stages and grade of the disease, as well as shorter DFS and OS of the patients." (PMID 21906360, 2011). "At the same time, 15 can be considered as an anticancer agent, due to the favorable interactions with the KLK5, a protein present in ovarian cancer." (PMID 34201422, 2021). "KLK5 was reported to be overexpressed in ovarian cancer, while in prostate cancer its expression levels were notably decreased compared with control tissues." (PMID 33150763, 2020). "In immunohistochemical studies, we have previously observed that KLK5 as well as KLK6 protein expression by stromal cells within the tumor tissue of ovarian cancer patients significantly contribute to tumorigenicity." (PMID 29095848, 2017). "In view of recent studies showing that elevated KLK5 and KLK7 values are associated with advanced stage, higher nuclear grade and a poor prognosis in ovarian cancer patients, the clinical impact of these two additional KLKs was tested." (PMID 25436002, 2015). "KLK8 protein present in blood (serum) indicates a favorable prognosis for the ovarian cancer patient while elevated protein levels of KLK5, 6, 10 and 11 are markers of a poor clinical outcome." (PMID 24294176, 2013). "KLK5 was found to be highly expressed in 58/142 (41%) of ovarian cancer samples while its level of expression was very low in normal ovarian tissues." (PMID 11237385, 2001). "KLK5 overexpression predicts a worse prognosis in various cancers, including cutaneous squamous cell carcinoma, colorectal adenocarcinoma, bladder tumors, and ovarian cancer, acting as an oncogene." (PMID 38090381, 2023). "Also, the level of KLK5 was intimately related with clinical parameters such as tumor grade and disease stage in ovarian cancer." (PMID 32076707, 2020). "Therefore, we aimed at exploring the interrelation between KLK5 and KLK7 mRNA levels as well as the clinical relevance of KLK7 expression in the same ovarian cancer patient cohort, which was previously used for KLK5 mRNA analysis." (PMID 33087135, 2020). "In ovarian cancer, both KLK5 and KLK7 expression levels were previously reported to be up-regulated in ovarian neoplasms, compared to benign and/or low malignant potential carcinomas, indicating that they may represent diagnostic factors in this tumor entity." (PMID 33087135, 2020). "In particular, the present study has confirmed earlier findings showing that KLK5 is associated with advanced and more aggressive disease, and that KLK7 may be a favorable prognostic marker in ovarian cancer." (PMID 25436002, 2015). "In addition, the KLK5 concentration in serum was reported to correlate with ovarian cancer patients' poor response to chemotherapy, and poor outcome." (PMID 21906360, 2011). "Furthermore, KLK5–8, 10, 11 and 13 are judged as promising predictive ovarian cancer biomarkers." (PMID 24294176, 2013). "We have thus hypothesized that KLK5 may be a new prognostic indicator in ovarian cancer." (PMID 11237385, 2001).
ovarian carcinoma (continued). "Several studies have shown that KLK5 and KLK7 serve as serological biomarkers and indicators of poor prognosis in breast and ovarian cancer." (PMID 33588911, 2021). "Activation of the TGFβ pathway was also observed in a proteomic analysis of the secretome of an ovarian cancer cell line engineered to overexpress KLK4, KLK5, KLK6 and KLK7." (PMID 33255452, 2020). "Another study showed that seven genes (KLK5-8, KLK10, KLK11, and KLK14) were elevated in ovarian cancer tissue samples and cell lines compared with the healthy ovary." (PMID 33150763, 2020). "Similar to KLK5, KLK6 is a biomarker for ovarian cancer, but is also overexpressed in colorectal cancers." (PMID 33150763, 2020). "High protein levels of KLK4–7 and KLK10 have been found in ovarian cancer tissues, while KLK5–8, KLK10, KLK11, KLK13 and KLK14 were found in ascites fluid from ovarian cancer patients as reviewed." (PMID 24043563, 2014). "We have reported that combined expression of KLK4, KLK5, KLK6, and KLK7 in OV-MZ-6 ovarian cancer cells regulates integrin expression, cell adhesion, and promotes a malignant phenotype." (PMID 27605189, 2013). "Specifically, higher expression of KLK5 isoforms with short 5′ UTRs, including KLK5-203, has been reported in ovarian cancer with respect to normal ovarian cells." (PMID 37828616, 2023). "KLK5 and KLK7 are majorly involved in skin desquamation, a process which may be similar to the shedding of tumor cells from the primary tumor in ovarian cancer leading to intraperitoneal dissemination." (PMID 33087135, 2020). "Besides, we observed pronounced correlations between KLK5 and KLK7 mRNA levels as well as between their antigen levels, providing good evidence for the coordinate expression of KLK5 with KLK7 in ovarian cancer." (PMID 33087135, 2020). "KLK4, KLK5, KLK6 and KLK7 have been found related to the prognosis of ovarian cancer." (PMID 27825132, 2016). "Recently, it was reported that reactivation of KLK5 reverted the malignancy of ES-2 ovarian cancer cells; however, no mechanistic insight has been provided." (PMID 24158494, 2014). "Elevated expression of KLK4, KLK5, KLK6, and KLK7 are linked to multi-cellular aggregation of ovarian cancer cells and non-responsiveness of patients to paclitaxel." (PMID 27605189, 2013). "Six kallikreins, KLK4, KLK5, KLK6, KLK7, KLK10, and KLK15, are markers of poor prognosis in ovarian cancer." (PMID 20354523, 2010). "A recent report showed a concordant higher expression of both KLK5 and KLK7 in ovarian carcinomas, especially late-stage serous carcinomas, compared with normal ovaries and benign adenomas." (PMID 20354523, 2010).
Netherton syndrome (15 papers, 2010 to 2025). Netherton syndrome (NS) is a skin disorder characterized by congenital ichthyosiform erythroderma (CIE), a distinctive hair shaft defect (trichorrhexis invaginata; TI) and atopic manifestations. "In keratinocytes from a Netherton syndrome patient,lead 7 significantly reduced the KLK5 activity and improvedepithelial barrier integrity, as shown by transepithelial electricalresistance." (PMID 41215618, 2025). "Targeted protease inhibition (KLK5/KLK7 blockade): If someone has Netherton syndrome, it means they lack the LEKTI protein, which leads to KLK5 and KLK7 acting uncontrollably and causing the skin barrier to break and become inflamed." (PMID 40734872, 2025). "High KLK5 activity has been related to pathological desquamation in Netherton syndrome and atopic dermatitis." (PMID 37828616, 2023). "In Spink5−/−Klk5−/−, Klk5 was genetically ablated on the Netherton background to provide proof of concept for drugging the KLK5 activity for pharmacotherapy of Netherton syndrome and, potentially, other diseases like atopic dermatitis." (PMID 35652924, 2022). "In agreement with the fact that LEKTI inhibits matriptase-dependent skin desquamation in Netherton Syndrome by the direct inhibition of KLK5 and our data shows that concomitant expression of LEKTI with matriptase rescues aberrant KLK5 expression." (PMID 34503205, 2021). "In this study, we revealed the in vivo roles of KLK5 and KLK7 using a set of mouse models that are simultaneously deficient for KLK5 and KLK7 on the genetic background of Netherton syndrome-like mouse model based on a mutation found in human patients." (PMID 28095415, 2017). "SPINK5 specifically inhibits KLK5, KLK7, and KLK14 activity, and mutations in SPINK5 cause Netherton Syndrome, a severe skin disorder." (PMID 28414719, 2017). "LEKTI can diminish the activities of epidermal serine proteases such as KLK5, KLK6, KLK7, KLK13, and KLK14 in skin, and a mutation in the SPINK5 gene is characteristic of Netherton syndrome, which presents with serious dehydration, itching, and chronic skin inflammation." (PMID 35955819, 2022). "Building on previous work showing the clinical potential of targeting Klk5 in Netherton syndrome, our work establishes KLK7 and ELA2 as promising targets for the treatment of Netherton syndrome patients through the activation of NRF2 and subsequent upregulation of SLPI." (PMID 32457102, 2020). "Importantly, the upregulation of KLK5 and KLK7 activity by loss of the endogenous KLK inhibitor serine peptidase inhibitor Kazal type 5 (SPINK5) causes atopic dermatitis‐associated diseases, including Netherton syndrome." (PMID 29311134, 2018). "Although the roles of KLK5 and KLK7 in inflammatory dermatoses like Netherton syndrome and atopic dermatitis have been revealed, their functions in wound healing are still unclear." (PMID 40147022, 2025). "In this direction, a skin equivalent (encompassing both epidermis and dermis) for SPINK5-sEDD (Netherton syndrome) was previously designed, to test the role of KLK7 and KLK5 gene silencing, or their chemical inhibition in reversing the disease phenotype." (PMID 40943523, 2025). "For example, a bispecific anti-KLK5/7 Fab antibody was raised against murine KLK5 and KLK7 with the potential to treat Netherton syndrome (NS)." (PMID 41516101, 2025). "In particular, the skin-derived KLK5, KLK7, and KLK14 have recently gained increasing attention as promising therapeutic targets in inflammatory skin disorders and cutaneous malignancies, such as the widespread atopic dermatitis and the rarer Netherton syndrome." (PMID 41516101, 2025).
atopic dermatitis (14 papers, 2010 to 2025). "Increased KLK5 activity hasbeen linked to atopic dermatitis (AD), a chronic inflammatory diseaseaffecting up to 20% of children, highlighting the need for therapiesthat restore barrier integrity." (PMID 41215618, 2025). "Transgenic models overexpressing Klk5 exhibit features of atopic dermatitis, including corneodesmosome degradation, detachment of the stratum corneum, and increased cytokine production." (PMID 40753921, 2025). "KLK5 is a serine protease involved in cell renewal and regulation of skin barrier function, and abnormal KLK-5 expression and the hyperactivation of KLK-5 are known to induce atopic dermatitis-like lesions in the skin." (PMID 36483564, 2022). "These inhibitors could also be important for the treatment of other more common diseases governed by upregulated KLK5, such as rosacea and atopic dermatitis." (PMID 40943523, 2025). "Moreover, the overactivation of KLK5 induces proinflammatory cytokines, such as TSLP and TNF-α, which are implicated in the development of dermatoses such as pruritus and atopic dermatitis." (PMID 29077044, 2017). "A monoclonal bispecific human anti-KLK5/KLK7-Fab antibody improved skin barrier function and reduced inflammation in mouse models of NS and atopic dermatitis." (PMID 41516101, 2025). "Finally, a bispecific KLK5/KLK7 antibody has been generated and tested in the mouse model of SPINK5-sEDD and atopic dermatitis." (PMID 40943523, 2025).
cervical cancer (6 papers, 2022 to 2025). A primary or metastatic malignant neoplasm involving the cervix. "Furthermore, the overexpression of KLK5 is linked to the aggressiveness of cervical cancer, and may explain why traditional treatments aren’t working." (PMID 35804810, 2022). "They further demonstrated that KLK5 inhibition in cervical cancer cells decreases radioresistance by downregulating G2/mitotic-specific cyclin-B1 (cyclin B1) expression and blocking the transition to the G2/M phase." (PMID 40072068, 2025). "Aberrant KLK5 expression has been identified in cervical cancer and significantly impacts tumor prognosis." (PMID 40509092, 2025). "The inhibition of KLK5 in cervical cancer cells decreases radioresistance by downregulating cyclin B1 expression and blocking the transition to the G2/M phase." (PMID 38651153, 2024). "Consequently, KLK5 can serve as a marker for assessing radiosensitivity and prognosis in cervical cancer patients." (PMID 38651153, 2024). "As a result, KLK5 could be a good predictor of cervical cancer prognosis." (PMID 35804810, 2022). "Herein, we demonstrated an aberrant expression of matriptase, KLK5, and KLK7 in human biopsies from patients with early cervical cancer (high-grade intraepithelial lesion - HSIL)." (PMID 40753921, 2025). "•Serine proteases KLK5, KLK7, and KLK14 are upregulated in HPV-driven cervical cancer." (PMID 40753921, 2025). "This study underscores the critical roles of serine proteases KLK5, KLK7, and KLK14 in cervical carcinogenesis, suggesting that these serine proteases are promising targets for the development of novel therapeutic strategies in cervical cancer." (PMID 40753921, 2025).
prostate carcinoma (6 papers, 2019 to 2025). A carcinoma that arises from epithelial cells of the prostate gland. "In conclusion, KLK2, KLK3, KLK4, KLK5, KLK11, and possibly KLK15 are important for normal prostate physiology but become reprogrammed in prostate cancer to drive tumor progression." (PMID 41516101, 2025). "However, other KLKs play a role in the prostate, such as KLK1, KLK5, KLK9, and KLK15, which are upregulated in prostate cancer." (PMID 41516101, 2025).
Erythema (5 papers, 2015 to 2025). Redness of the skin, caused by hyperemia of the capillaries in the lower layers of the skin. "Innate immune activation leads to upregulation of keratinocyte-derived toll-like receptor 2 (TLR2) promoting the expression of the antimicrobial peptide cathelicidin, which is subsequently activated to bioactive LL-37 by kallikrein 5 (KLK-5) protease, leading to erythema and angiogenesis." (PMID 40410272, 2025). "In this study, we investigate whether the ability of CC to inhibit KLK5 could influence the activation of cathelicidin and induction of inflammatory response and erythema in human epidermal keratinocytes." (PMID 33256158, 2020). "Mechanisms that regulate this network of KLK5 in the epidermis are important in regulating epidermal homeostasis through normal physiological interactions, and understanding these is an important research area, as changes in proteolytic balance can lead to skin inflammation and erythema." (PMID 33256158, 2020). "In PP rosacea, serine protease kallikrein-5 (KLK5) and two abnormal cathelicidin peptides (LL-37 and FA-29) are upregulated in the skin and induce erythema and vascular dilatation when injected in mouse skin." (PMID 27347521, 2015).
oral squamous cell carcinoma (5 papers, 2016 to 2021). "Another evidence is that KLK5-mediated activation of PAR-2 in oral squamous cell carcinoma leads to the activation of NF-κB signaling, which increases expression of inflammatory cytokines and suppresses anti-inflammatory tumor suppressor microRNAs." (PMID 27612426, 2016). "In bladder carcinoma cells, siRNA-mediated inhibition of KLK5 expression led to a significant reduction of invasion in Matrigel-based assays, whereas in oral squamous cell carcinoma cells silencing of KLK5 enforced cell-cell adhesion that promoted loss of junctional integrity and, hence, metastasis." (PMID 31307411, 2019).
skin inflammation (5 papers, 2016 to 2026). "Furthermore, the decreases in KLK5 and IL-8 in the probiotic group suggested that probiotic administration could alleviate skin inflammation." (PMID 39475254, 2024).
colon cancer (4 papers, 2009 to 2022). "Many in vitro studies have shown that KLK6 may undergo autoactivation or become activated by other proteases including other KLKs, such as KLK14 and KLK5, for which overexpression in human colon tumors has been demonstrated in our previous report and in ongoing work (unpublished data)." (PMID 35883559, 2022). "Nine KLKs (KLK5-8, KLK10, KLK11, KLK13-15) were measured using ELISA assays in cytosolic extracts of 122 colon cancer tissues and their nearby normal mucosa, obtained during surgery." (PMID 19367279, 2009).
colorectal cancer (4 papers, 2016 to 2024). A primary or metastatic malignant neoplasm that affects the colon or rectum. "Growing evidence suggests that KLK5 is upregulated in numerous types of cancers such as colorectal cancer, gastric cancer, and oral cancer and is implicated in carcinogenesis." (PMID 36835153, 2023).
Hyperkeratosis (4 papers, 2015 to 2022). Hyperkeratosis is a histopathological term defining a thickened stratum corneum and may be present in many different skin conditions, with many possible overlaps. "Hyperkeratosis in epidermis is thoroughly regulated by serine proteases such as KLK5 or KLK7 and serine protease inhibitors such as SPINK5." (PMID 33652999, 2021). "We found that although Klk5-/-Sp5A135X/A135X pups showed normal differentiation at P0, over time they developed hyperplastic epidermis with acanthosis, severe intrafollicular hyperkeratosis and the skin was infiltrated by mast cells." (PMID 28095415, 2017). "Collectively, these observations show that LCE can prevent hyperkeratosis and maintain moisturizing function by increasing the expression of LEKTI and inhibiting the activation and expression of KLK5, thereby preserving bonds between keratinocytes." (PMID 35955819, 2022). "Then, KLK5 and KLK7 induced proteolysis of desmocollin 1 (DSC-1), one of corneodesmosonal components, which is involved in hyperkeratosis." (PMID 33652999, 2021). "Furthermore, this DNCB-induced increase in KLK5 expression and its suppression by LCE corresponded to observed degrees of hyperkeratosis." (PMID 35955819, 2022). "In contrast, histology examination of skin sections from Spink5-/-Klk5-/- mice showed neither acanthosis nor hyperkeratosis, nor microscopic separation of the stratum corneum/stratum granulosum." (PMID 26390218, 2015).
Allergy (3 papers, 2015 to 2024). An allergy is an immune response or reaction to substances that are usually not harmful. "Collectively, these data demonstrate that Klk5 ablation is sufficient to block the development of cutaneous inflammation and allergy in the context of Lekti-deficiency." (PMID 26390218, 2015). "These animals reproduced major features of NS, including increased proteolytic activity in the skin, a severe skin barrier defect with cutaneous and systemic allergy and inflammation, identifying KLK5 as an important contributor of NS pathogenesis." (PMID 26390218, 2015). "Surprisingly, we found unchanged levels of the allergy-associated cytokine TSLP in skin of Spink5 cKO mice, which contradicts previous studies with Spink5-/- mice, showing TSLP up-regulation in keratinocytes through KLK5-mediated PAR-2 activation." (PMID 38316920, 2024). "The expression of Ccl8, known to attract actors of allergy and inflammation, was elevated in both Spink5-/- and Spink5-/-Klk5-/- skin, whereas Ccl20, a chemoattractant for CCR6+ cells including dendritic cells and Th17 cells, showed a significant increase only in Spink5-/- skin." (PMID 26390218, 2015). "Quantitative RT-PCR analyses and immunostainings revealed absence of inflammation and allergy in Spink5-/-Klk5-/- skin." (PMID 26390218, 2015).